FOXP3 (forkhead box P3)
Diseases named in the same sentence as FOXP3 in open-access papers (continued):
Sharing a sentence is not in itself a finding about the gene and the disease.
tumor (continued). "Stromal FoxP3+ and CD8+ cell densities were moderately positively correlated in both “immune-desert” (Spearman correlation coefficient = 0.59, p = 0.001, n = 43) and “inflamed” tumours (Spearman correlation coefficient = 0.407, p = 0.014, n = 36)." (PMID 35140715, 2022). "We also observed increases in the percentages of tumor-infiltrating lymphocytes (TIL) producing IFNγ and activation marker Granzyme B (GZMB), and a reduced fraction of FOXP3+ T regulatory cells, whereas the fraction of CD11b+ Ly6G+ neutrophils and F4/80+ CD11b+ macrophages remained constant." (PMID 35915084, 2022). "A moderate correlation was observed between frequencies of FoxP3+ Tregs and CD4+LAG-3+ T cells in PBMCs of CRC patients, and it was found to be stronger in advanced tumor stages compared to early stages (r = −0.022, p = 0.945 [early]; r = 0.488, p = 0.039 [advanced])." (PMID 36146549, 2022). "The functions of FOXP3, JAK3, and IKZF3 are widely researched in the field of tumor immunology." (PMID 35719936, 2022). "IL‐17A+FOXP3+ Tregs are a subpopulation of suppressive Tregs, which could be promoted by TGF‐β during tumor progression." (PMID 35474948, 2022). "This lack of consistency is likely due to differences in the compartment studied (peripheral blood vs bone marrow), different immunophenotypic definitions of Tregs (CD4+FoxP3+, CD4+CD25hi, CD4+CD25+FoxP3+, CD4+CD25+CD127−), and interpatient tumor heterogeneity." (PMID 36421358, 2022). "The TIL Foxp3 survival prediction was to some extent independent of TNM stages, age, and gender as well as levels of tumor nuclear polymorphism, tumor invasion, desmoplasia, general lymphocyte infiltration, and TAM levels." (PMID 35326661, 2022). "Collectively, these findings suggest that tumor FoxP3 expression has a better prognostic potential in NSCLC and that, in combination with intratumoral Tregs, the absence of the tumor FoxP3 is correlated with high-risk patients." (PMID 35874749, 2022). "Given that some studies have reported that FOXP3 can regulate the expression of VEGF and other molecules related to angiogenesis, it is reasonable to believe that FOXP3 can participate in the regulation of tumor metastasis by TCM." (PMID 36235242, 2022). "Moreover, in a preclinical in vivo model of SCLC, the tumor impairment observed with the combined use of PARPi and anti-PD-L1 was accompanied by reduced CD4+FOXP3 Treg frequency and amplified cytotoxic CD8+ T cell response." (PMID 36428727, 2022). "In the current investigation, Pirc tumor SPI samples had increased expression of β2m, interferon-γ and Canx as compared to Pirc tumor SPI3d and Pirc tumor AIN groups, and decreased levels of Foxp3, Iκbα and Survivin, implicating NFκB signaling and apoptosis induction." (PMID 35159382, 2022). "This CCNP, in response to PTT, could induce tumor necrosis and release whole-cell tumor antigens, activate CD8+ cytotoxic T cells and reduce regulatory Foxp3+ T cells, and further enhance antitumor immunotherapy." (PMID 36105816, 2022). "The results showed that the number of Foxp3+ (P < 0.001), OX40+ (P = 0.001) and CD8+ T (P = 0.008) lymphocytes in poorly differentiated areas was significantly higher than that in the well-differentiated areas of the tumor, respectively." (PMID 36081505, 2022). "As widely reported, Foxp3 and IDO1 are co-expressed in a series of tumor tissues, suggesting that IDO1 is involved in the differentiation of T cells into Foxp3 Tregs and promotion of tumor growth." (PMID 35681736, 2022). "Analysis of tumor infiltrating immune cells by FACS indicated a significant increase of Foxp3+/PD-1− Treg cells, but no changes in the other cell subsets." (PMID 36537914, 2022). "Moreover, they can predict the presence of Foxp3+ and CD3+ lymphocytes in the invasive margin of a tumor." (PMID 35915403, 2022).
tumor (continued). "We next examined the levels of tumor regulatory T cells (Tregs, CD3+CD4+Foxp3+), which could suppress the antitumor immune responses of cytotoxic T lymphocytes and induce an immunosuppressive microenvironment." (PMID 35931666, 2022). "Noteworthy, FGL1 is positively associated with CD4+ T cell levels within the tumor, while it can also support the expression of CD3D and prevent that of FOXP3; hence, FGL1 may support T cell tumor infiltration and function in the cancer microenvironment." (PMID 36268014, 2022). "To further investigate the mechanism by which tumor-infiltrating lymphocytes were affected by miR-128-3p, we found that miR-128-3p knockdown or overexpression increased or decreased the differentiation of CD4+ CD25+ Foxp3+ Tregs." (PMID 34968167, 2022). "Notably, the ratio of Treg populations in B7x+ MC38 tumors was elevated in comparison to the Foxp3− conventional CD4+ T cell and CD8+ T cell populations, indicating that B7x was shifting the immune landscape of the tumor to a more suppressive milieu." (PMID 35523809, 2022). "Furthermore, HPV-positive primary lesions had a higher percentage of FoxP3+ Treg cells within a 20 μm radius from CD8+ CTL, both in the stromal and tumor regions." (PMID 36123711, 2022). "Cancer-derived miR-214, for instance, can promote the proliferation of CD4+ CD25 high Forkhead Box P3 (FoxP3) + Regulatory T cells (Tregs) by addressing PTEN and stimulating IL-10 production, resulting in host immune repression and accelerated tumor progression." (PMID 36793341, 2022). "However, there are more Foxp3+Treg cells and less IFNγ+TH1 cells, but similar TH2 and TH17 cells in Piezo1-/- compared with WT bearing-tumor mice." (PMID 35993548, 2022). "A significant anti-tumor effect was observed in the irradiated and abscopal tumors, thus we next examined the immune microenvironment including CTL (CD8+, Granzyme B+ (GzmB+) in CD45+) and Treg (CD4+, FoxP3+ in CD45+)." (PMID 35565217, 2022). "For example, exercise performed for eight weeks prior to subcutaneous 4T1 injection reduced tumour growth rate by 17%, alongside reductions in FoxP3+ TREG cells within tumours compared to non-exercising rodents." (PMID 35359426, 2022). "Gal-9 expression on TILs was significantly correlated with CD4 on TILs (P = 0.025), CD8 on TILs (P = 0.001), FOXP3 on TILs (P = 0.022), OX40L on tumor cells (P = 0.03), OX40L on TILs (P = 0.00018), PD-1 on TILs (P = 0.002), PD-L1 on tumor cells (P = 0.026), and PD-L2 on tumor cells (P = 0.048)." (PMID 36263183, 2022). "In a mouse melanoma model GITR signaling destabilized Treg by reducing Foxp3 expression in intratumoral Tregs but not in circulating one which improved anti-tumor immunity." (PMID 36591244, 2022). "Statistics of CD8/FoxP3 ratio in tumor tissue showed that the infiltration rate of CD8+ T cells was increased after the combination of osimertinib and bevacizumab, while the infiltration rate of FoxP3+ T cells was decreased." (PMID 35783156, 2022). "Moreover, the tumor-derived exosomes induced Treg expansion, resulting in the generation of Tim3 (Low) Tregs with increased expression of CD25 and FOXP3." (PMID 36233088, 2022). "High levels of Foxp3+ Tregs in the tumor environment and the absence of Arg2 significantly impacted the survival of patients with head and neck squamous cell carcinoma." (PMID 35371055, 2022). "As Tregs serve to regulate excessive immune reactivity to prevent auto-immunity, it is theorized that the presence of high densities of FoxP3+ Tregs in HNSCC could indicate an active, robust antitumor immune response, contributing to improved tumor control." (PMID 36698398, 2022). "Tumor infiltrating immune cell profile analyses also revealed the reduction of immuno-suppressive CTLA-4+CD8+ cells and CD4+CD25+Foxp3+ Tregs, whereas the percentage of tumor infiltrating cytotoxic CD8+ T cells and the ratio of M1/M2 macrophages increased in nCHI3L1 Ab treatment group." (PMID 34987649, 2022).
tumor (continued). "Furthermore, a strong positive correlation was found between levels of FoxP3+Helios+ Tregs and CD4+CTLA-4+ T cells (r = 0.695, p = 0.0007) in tumor tissues." (PMID 35455287, 2022). "Moreover, a high frequency of FoxP3+ Tregs within the tumor leads to a promising outcome in CRC, suggesting that FoxP3+ Tregs are one of the most useful predictive indicators of disease prognosis in CRC patients." (PMID 35455287, 2022). "In immunofluorescence double immunohistochemical staining experiments, whilst GrB+ cells localized to the same region as FoxP3+ Tregs in the tumor–stroma interface, no clear colocalization was observed." (PMID 36551965, 2022). "They further discovered that the IM is multifaceted and may serve pro- and anti-tumor functions simultaneously with higher CD8+ expression and more FOXP3+ cells." (PMID 35228530, 2022). "Moreover, a high frequency of FoxP3+ Tregs within tumor lead to a promising outcome in CRC, suggesting that FoxP3+ Tregs are one of the most useful indicators for predicting the prognosis of CRC." (PMID 35655158, 2022). "The results showed that the H-XRT + α-TIGIT + α-PD1 group was capable of increasing the percentages of total CD4+ T-cells, CD4+ Foxp3+ Tregs, as well as total CD8+ T-cells at the unirradiated secondary tumor site compared to the Ctrl group (p = 0.05, p = 0.0251, p = 0.0111, respectively)." (PMID 35008385, 2022). "FOXP3 overexpression, on the other hand, enhanced tumor size by increasing the percentage of CCR4+ Tregs in the peripheral circulation as well as at the tumor site." (PMID 35222362, 2022). "To analyze whether different drugs can promote the increase of tumor-infiltrating T cells, we examined the proportion of CD4+ and CD8+ T cells, NK1.1, and CD4+Foxp3+ Treg in the spleen of mice." (PMID 35875081, 2022). "For in vivo study, the xenograft tumor tissues of the shSEMA4B and shCtrl group were disaggregated in single-cell suspensions and stained with cell surface markers including CD4, CD25, CD11b, and intracellular markers FOXP3 and Gr1." (PMID 35676688, 2022). "Similarly, PD-L1 expression in stromal or tumor cells is inversely correlated with FOXP3+ cell density in CRC patients, further reinforcing the fundamental role in modulating regulatory T cells (Treg) in the tumor microenvironment." (PMID 36614038, 2022). "Also, positive correlations were found between frequencies of FoxP3+Helios− Tregs and CD4+PD-1+ T cells in PBMCs and TILs in advanced tumor stages, and a positive correlation in NILs only in early tumor stages." (PMID 36146549, 2022). "CB-specific T cells primed in wild-type mice and transferred into tumor-bearing Batf3–/– mice did not acquire Foxp3 or the Klrg1+Lag3+ subset." (PMID 35393950, 2022). "Tumor cells obtained after the treatment schedule were harvested, mechanically and enzymatically digested, and stained with anti-CD3, anti-CD8, anti-CD4, and anti-FOXP3 antibodies." (PMID 35991316, 2022). "In conclusion, these studies show that a high level of FOXP3 in NSCLC could play a vital role by participating in different signaling pathways, ultimately resulting in tumor EMT." (PMID 36235242, 2022). "Compared with tumor tissue, adjacent normal tissue showed a significantly higher CD8/FOXP3 ratio." (PMID 35222387, 2022). "FOXP3 and CD8 staining patterns in the tumor and tumor stroma." (PMID 35358193, 2022). "This is presently verified studying tumor CD3+ cells and Foxp3 (+) TILs." (PMID 35326661, 2022). "FOXP3 can also reduce the chemotaxis of CXCL12 (C-X-C motif ligand 12) by inhibiting the expression of CXCR4, which leads to the inhibition of the distant metastases of tumors, and participates in the inhibition of tumor cell adhesion and invasion." (PMID 36235242, 2022).
tumor (continued). "Spatial distribution imaging analysis (multiplex immunofluorescence) suggested that a small fraction of CD8+PD-1+ T cells are also GITR+ (FoxP3–) within inflamed and excluded compartments of HNSCC, including the tumor, stroma and tumor-proximal lymph node aggregates." (PMID 35256819, 2022). "Our analyses from the combined tumor regions (TC and IM) have demonstrated that the majority of patients’ tumors infiltrated by high numbers of CD8+ cells are also co-infiltrated by high densities of CD163+ and/or FoxP3+ cells." (PMID 36551693, 2022). "The decrease in tumor size is accompanied by a decrease in CCR4+ Treg generation both in the peripheral circulation and at the tumor site, demonstrating that FOXP3 transcriptionally activates CCR4 in both in vitro and in vivo settings." (PMID 35222362, 2022). "Therefore, this nanoplatform dramatically reversed CD206+F4/80+CD11b+ TAMs to CD86+F4/80+CD11b+ M1 phenotype, decreased immunosuppressive FOXP3+CD4+CD25+ Treg cells, and increased anti‐tumor IFN‐γ+CD8+ T cells in B16F10 and 4T1 tumor‐bearing mice." (PMID 37323705, 2022). "The immunosuppressive cells in the TME of PC are mainly tumor associated macrophages (TAMs), myeloid-derived suppressor cells (MDSCs), and tumor-infiltrating lymphocytes (TILs), which are composed of CD4+ T cells, CD8+ T cells, and FOXP3+ regulatory T cells (Tregs)." (PMID 36106025, 2022). "Moreover, in the tumor microenvironment, Tregs express increased levels of ICOS and Foxp3 and secrete higher levels of IL-10 and TGF-b." (PMID 36591244, 2022). "Therefore, among CD3 + T cells, the numbers of CD3 + /CD8 + cytotoxic T cells and CD3 + /CD4 + helper T cells in tumor lesions of MB49 cell-implanted mice were evaluated by FACS and IHC analyses using antibodies to CD8, CD4, and FoxP3." (PMID 35787261, 2022). "On the other hand, CD4 + T-helper 2 (Th2) cells, including Foxp3+ Treg cells, inhibit CTL function, support B lymphocyte proliferation, and may promote anti-inflammatory immune response, thereby promoting tumor growth." (PMID 35242718, 2022). "FOXP3 and CD8 tumor infiltrating lymphocytes (TILs) significantly contributed to PD-L1 prediction." (PMID 36347854, 2022). "This is in accordance with the lack of correlation between CD4+CD25+ Foxp3+ infiltrating Tregs and the tumor volume both in lean and obese mice." (PMID 35472214, 2022). "In addition, regular exercise performed before and after subcutaneous injection with Hepa 1-6 liver cancer cells reduced tumour infiltrating CD25+FoxP3+ TREG cell proportion, alongside a 19% reduction in tumour growth." (PMID 35359426, 2022). "In addition, a recent study has demonstrated that IL-32 enhanced the anti-tumor activity by promoting IFN-γ expression in CD8+ T cells, while suppressing the immune responses by inducing Foxp3+ Tregs cells, indicating its contradictory role in the TME of ESCC." (PMID 36698392, 2022). "Interestingly, we found that CD4+FoxP3+Helios+ Treg subset and CD4+FoxP3−Helios− T cell subset in the tumor microenvironment (TME) contributed differently to the DFS in CRC patients." (PMID 35655158, 2022). "Although assessment of the immune landscape is technically challenging in single biopsies of the primary tumor, high combined mean densities of CD8+, FOXP3+, and PD‐1+ TAICs in the tumor epithelium and tumor stroma compartments are associated with response to nCRT." (PMID 34743329, 2022). "Interestingly, in our study we also observed that SBRT alone resulted in increased tumor densities of CD3+ T cells and FoxP3+ Tregs, as well as CD204+ macrophages." (PMID 35055015, 2022). "The authors concluded that the imbalance of Th17/ FoxP3-expressing T cells may play critical roles in the development and progression of UCC and that Th17 cells may promote tumor progression by fostering angiogenesis." (PMID 34553029, 2021).
tumor (continued). "In addition to recruitment of natural Treg to the tumor stroma, TAMs are also involved in the induction of Treg cells in the TME through regulation of Foxp3 via IL-10 and TGF-β signaling." (PMID 34771482, 2021). "Tumour infiltrating CD8+ T cells expressed high levels of PD-1 and CD4+ T cells expressed FoxP3 and CTLA4, suggested that immune suppression in the tumour microenvironment may be responsible for downregulation of cytotoxic T cell activity in the tumour." (PMID 34359633, 2021). "Since FoxP3 is predominantly expressed in Tregs, our data implied that there was no substantial increase of Treg populations within EGFR overexpressing tumours relative to wt EGFR tumours." (PMID 35052732, 2021). "The KPROR1 tumor develops a TME similar to a cold tumor subtype of human NSCLC characterized by few lymphocyte infiltration, abundant myeloid infiltration, and development of tertiary lymphoid structures enriched with Foxp3+ Tregs in a low CD8/Treg ratio." (PMID 34332618, 2021). "Treg are defined as a T helper cell subpopulation characterized by the co-expression of CD4, CD25, and in large parts of FoxP3, which inhibit the activation and differentiation of CD4+ and CD8+ T cells, subsequently impairing reactivity against autologous and tumor-expressed antigens." (PMID 33430105, 2021). "Tumor-suppressing effects inhibit cell proliferation (p15, p21, p57, 4E-BP1), apoptosis (Bim, DAPK, GADD45β), and autophagy (ATG5, ATG7, Beclin-1), suppress inflammation (Foxp3) and block angiogenesis (Thrombospondin)." (PMID 33823905, 2021). "Interestingly, the percentage of Tregs (CD4+Foxp3+) was upregulated in the RFA and cryo-thermal treated groups compared with the tumor-bearing mice, and the proportion of Tregs in the cryo-thermal treated group was much higher than that in the RFA group." (PMID 34576115, 2021). "More interestingly, in a transgenic DEREG xenograft model (selective depletion of Tregs using diphtheria toxin injection), the transient depletion of FOXP3+ Tregs, following nonablative oligofractionated irradiation, improved the anti-tumour effect." (PMID 34206956, 2021). "Taken together, our results suggest that FOXP3 functions as a novel regulator of ATF3 and that this novel event may be involved in tumor development and progression." (PMID 34768829, 2021). "A study reported that in lung adenocarcinoma tumor growth was compromised in PCAF−/− mice, with reduced infiltration of CD4+Foxp3+ Treg cells but increased infiltration of host CD8 T cells, indicating that targeting PCAF reduces tumor volume and improves anti-tumor immunity." (PMID 34880761, 2021). "IL-32 may have a contradictory role in the TME such as it promotes IFNγ expression in CD8+ T cells, which enhances the antitumor activity, but at the same time induces Foxp3 expression in CD4+ T cells, which suppresses the tumor immune response." (PMID 34414188, 2021). "The only variables associated with overall survival were the lack of PTEN expression in tumor cells and the number of FOXP3+ cells in the stroma." (PMID 34362334, 2021). "On immune cell population, the CD8+ count was lower and FoxP3+ count was higher in tumor than non-tumor region, suggesting a deregulated immune microenvironment in the tumor region when compared with non-tumor region." (PMID 34257613, 2021). "Activation of FOXP3 could facilitate the Wnt-β-catenin signaling pathway in epithelial–mesenchymal transition (EMT), tumor growth, and metastasis of LUAD." (PMID 33510968, 2021). "One is antitumor cells mainly composed of CD4+ Th1 cells, CD8+ cytotoxic T lymphocytes (CTLs), NK cells, M1 macrophages, and dendritic cells, while the other is capable of promoting tumor growth and includes CD4+ FOXP3+ T cells (Tregs), CD4+ Th2 cells, and M2 macrophages." (PMID 34888385, 2021). "Tumoral PDL1 expression and increased density of intratumoral CD8+ lymphocytes and FoxP3+ lymphocytes may positively impact on survival in a subset of MCCs." (PMID 34071045, 2021).